IL6 (interleukin 6)
Diseases named in the same sentence as IL6 in open-access papers (continued):
Sharing a sentence is not in itself a finding about the gene and the disease.
myeloma (continued). "Interaction of myeloma cells with bone marrow stromal cells (BMSCs) via some key factors (SDF-1, TGFβ, IFNγ, IL6, and TNFα, etc.), induces pleiotropic anti-apoptotic mechanisms, thereby rendering multiple myeloma cells resistant to established therapeutic regimens." (PMID 28032590, 2017). "In addition, it was reported that berberine suppresses multiple myeloma cell growth by reducing miR-21 through IL6/Stat3 regulation." (PMID 29113353, 2017). "Interleukin-6 (IL-6) is an essential growth factor for myeloma cells." (PMID 29340073, 2017). "It is reported that IL-1β could promote tumor growth by inducing the release of downstream molecule IL-6 in patients with multiple myeloma." (PMID 29312552, 2017). "Interleukin-6 (IL-6) is a critical growth factor for myeloma cells." (PMID 29340073, 2017). "Since IL-6 is involved in early myeloma-stroma interaction and survival of neoplastic cells, IL-6 therapy at earlier stages of the disease might be more beneficial." (PMID 28099912, 2017). "In particular, paracrine regulation of IL-6 stimulates myeloma cell proliferation in patients." (PMID 28467797, 2017). "Researchers also found that several human multiple myeloma cell lines could spontaneously produce IL-10 up to 179 pg/ml and their IL-10 production could raised up to 1626 pg/ml when they were stimulated by IL-6." (PMID 28234961, 2017). "Additionally, IL-6 induced STAT3 phosphorylation in U266 multiple myeloma cells were found inhibited by TQ along with c-Src and JAK-2 activation." (PMID 28983249, 2017). "IL-6 upregulates Mcl-1 expression via activated STAT3 signaling in myeloma cells." (PMID 29340073, 2017). "This study focused on the role of IL-10 in MM cell line proliferation and resistance to anticancer drugs, considering that there are numerous reports on the role IL-6 in survival and proliferation of multiple myeloma (MM) cells through the phosphorylation of STAT3." (PMID 27418139, 2017). "In one study, baicalein inhibited myeloma cell proliferation by suppressing IL-6 signaling." (PMID 27042290, 2016). "The presence of CD45 within lipid rafts is responsible for IL-6 induced proliferation in myeloma." (PMID 27579617, 2016). "The role of cytokines especially IL6 has been magnified in renal cell carcinoma cells which may stimulate myeloma cells and myeloma cells decrease after nephrectomy." (PMID 27047652, 2016). "Such impairments could be the result of the increased production of myeloma-derived cytokines in the BM milieu, including IL-10, IL-6, and transforming growth factor (TGF)-β." (PMID 27618026, 2016). "The interplay of TGF-β and IL-6, expressed at high levels in the bone marrow of myeloma patients, may affect generation of Th17 cells both directly or via engagement of other pro-inflammatory cytokines and thereby modulate antitumor immune responses." (PMID 26784207, 2016). "Such discriminate associations also suggest that extracellular domains of CD45 isoforms may differentially promote association of the intracellular molecules with specific ability to regulate IL-6 signaling in myeloma." (PMID 25781885, 2015). "In multiple myeloma, Bim expression is downregulated by IL-6 and adhesion to fibronectin that might be related to Akt activation." (PMID 26405162, 2015). "Furthermore, Lyn and downstream protein kinase C (PKC) can be activated by IL-6 only in CD45+ myeloma cells." (PMID 25781885, 2015). "Recent data reported that human multiple myeloma cells secrete microvesicles able to promote in vitro and in vivo angiogenesis by stimulating the endothelial cells to proliferate, invade and secrete IL-6 and VEGF." (PMID 25944696, 2015). "The pivotal role of cholesterol in IL-6-induced STATs activation and myeloma cells proliferation suggests that administration of cholesterol-depleting drugs could be a potential therapeutic strategy against IL-6-induced myeloma cell proliferation." (PMID 25781885, 2015). "IL-6 can enhance the translation of c-Myc in multiple myeloma cells." (PMID 26508814, 2015).
myeloma (continued). "In conclusion, we propose a model of CD45 isoforms-mediated IL-6-induced myeloma cells signaling." (PMID 25781885, 2015). "Importantly, kinase-dead HCK mutants, or treatment with the SFK inhibitor PP2, reduced IL6-induced tyrosine phosphorylation of intracellular signaling proteins and significantly decreased myeloma cell survival and proliferation." (PMID 26087188, 2015). "Furthermore, both inhibitors triggered similar effects on IL-6-induced proliferation confirmed by both the myeloma cell line and primary cells." (PMID 25781885, 2015). "First, we examined whether IL-6 signaling molecules are distributed in lipid rafts of myeloma cells." (PMID 25781885, 2015). "According to the previous study, it was hypothesized that elevated PTH may mediate the induction of multiple myeloma (MM) through the downstream biologic effects of interleukin 6 (IL-6)." (PMID 24967406, 2014). "Consistently, NF-κB activation upregulates the expression of IL-6 during multiple myeloma." (PMID 25084093, 2014). "Recent studies found elevated levels of RANK ligand in combination with MIP1-α or IL-6 in high frequencies of patients with multiple myeloma, and experimental results suggest that the relationship between these transcription factors are important to osteoclast proliferation." (PMID 25470373, 2014). "Sakai A, reported a case of association of multiple myeloma and clear cell carcinoma of the kidney, and has advanced the hypothesis of a local secretion of growth factor especially IL-6 and its participation in the induction of multiple myeloma." (PMID 25810804, 2014). "Down-regulation of interleukin 6 (IL6) by berberine might lead to inhibition of miR-21 transcription through STAT3 down-regulation in multiple myeloma." (PMID 25000828, 2014). "Anakinra decreased IL-6 levels but left numbers of myeloma cells unaffected." (PMID 25905009, 2014). "Some investigators have concluded that the leukocytosis is in response to the myeloma because monoclonal B-cell clones in myeloma can produce cytokines which are able to activate stromal cells to produce IL-6, IL-7, and IL-11 to stimulate T lymphocytes to produce IL-3 and GM-CSF." (PMID 25143840, 2014). "Thus, despite cell-intrinsic constitutive NFκB activation, multiple myeloma cells depend on an extrinsic source of IL6 for their development and survival." (PMID 25132836, 2014). "In low density cultures, both the addition of IL-6 or APRIL led to increased yield of myeloma cells three days later, regardless whether the cultures contained 1% or 5% FCS." (PMID 25272036, 2014). "While IL-6 signals via at least 3 pathways in multiple myeloma, namely STAT3, ERK1/2, and AKT, we first biologically validated the impact of YM155 on IL-6/STAT3-signalling, finding a concentration-dependent decrease of phospho-STAT3 in both cell lines after 24 hours under normal growth conditions." (PMID 25296978, 2014). "Thus, targeting IL-6 triggered MCL-1 modulating molecules offers potential therapeutic approach to treat multiple myeloma." (PMID 25422792, 2014). "This could potentially result from the ability of OBs to secrete IL-6 in coculture system with myeloma plasma cells, therefore, inducing MM cell growth." (PMID 23818912, 2013). "Therefore, NF-κB activation in BMSCs enhances positive loop with adherent multiple myeloma cells by secretion of growth factors such as IL-6, TNFα, and HGF." (PMID 24151609, 2013). "In conclusion, blockage of JAK/STAT-mediated NF-κB activation was highly effective in controlling the growth of MM cells and, consequently, an inhibitor of TNFα-mediated IL-6 secretion would be a potential new therapeutic agent for patients with multiple myeloma." (PMID 24151609, 2013). "The second mechanism described in myeloma cells was induced by IL-6." (PMID 23533689, 2013). "Indeed, IL-6 produced by bone marrow stromal cells is an autocrine growth factor for human myeloma cells and it is involved in the genesis of several of the clinical symptoms observed in MM patients." (PMID 24489445, 2013).
myeloma (continued). "Furthermore, HGF not only promotes growth, migration, and survival of myeloma cells, it also potentiates IL-6 effects." (PMID 24326130, 2013). "In addition to TNFα, IL-6, produced from multiple myeloma cells as well as bone marrow stromal cells, is also a major growth factor for tumor cells regulating various biological signaling." (PMID 24151609, 2013). "Among them, IL-6 is a potent myeloma cell growth factor, with both in vitro and in vivo activity." (PMID 23936794, 2013). "Additionally, a significant correlation was noted between BAFF and IL-6 serum levels, suggesting the important role of IL-10 in myeloma progression." (PMID 23936794, 2013). "Patients of POEMS have higher levels of IL-1B, TNF-alpha and IL-6 as compared to multiple myeloma." (PMID 24349810, 2013). "So, we hypothesized that TNFα is one of the major factors that regulate IL-6 secretion from multiple myeloma cells." (PMID 24151609, 2013). "This gene is involved in the IL-6 signaling pathway which is important in myeloma cell survival." (PMID 22253745, 2012). "The interplay of TGF-β and IL-6, expressed at high levels in the bone marrow of myeloma patients, may affect generation of Th17 cells both directly or via other pro-inflammatory cytokines and thereby modulate antitumor immune responses." (PMID 22489248, 2012). "Osteoclasts may also support the growth of myeloma cells through secretion of IL-6 and osteopontin, and by adhesive interactions, stimulating the proliferation of malignant plasma cells." (PMID 22363428, 2012). "Hypermethylation of the promoters of various tumor suppressors such as miR-124-1 (a target of CDK6), miR-203 (a target of cyclic-responsive element-binding protein which increases proliferation), and miR-29b (a target of Mcl-1 which antagonizes IL-6) increase the tumorigenicity of myeloma cells." (PMID 23259069, 2012). "In addition, baicalin is unable to duplicate the baicalein-induced activation of the IL-6-mediated signaling cascade seen in human myeloma cells." (PMID 22607709, 2012). "In one of the largest studies, 12 patients with refractory myeloma were treated with a chimeric human-mouse IL-6 antibody and 11 patients had stabilization of disease but none achieved a clinically significant response (defined as greater than 50% reduction in M protein)." (PMID 24213115, 2011). "IL-6 has been proposed as the major myeloma plasma cell growth factor." (PMID 21941412, 2011). "IL-6 is an important growth factor for lymphoma and multiple myeloma cells in vitro and in vivo." (PMID 22114899, 2011). "By explicitly considering interleukin-6 (IL-6) and multiple myeloma-bone marrow stromal cell (MM-BMSC) adhesion related pathways, a new tentative MM-bone model is developed, and two positive feedback cycles in MM-bone interactions can then be identified in this model." (PMID 22110661, 2011). "Overexpression of IL-6 appears to play a role in the pathogenesis of many cancers, including breast, renal cell, colon, prostate, bladder, in addition to B-cell malignancies, most notably myeloma." (PMID 24213115, 2011). "Although inhibiting IL-6 signaling through its high affinity receptor promotes apoptosis of MM cells when cocultured with BMSCs, some myeloma cells survive suggesting that the marrow microenvironment stimulates IL-6-independent pathways that exert a prosurvival effect." (PMID 20204067, 2010). "Several human tumour cell lines have been reported to produce IL-6, and an IL-6/IL-6R autocrine loop has been described in several tumours, including oesophageal carcinoma, multiple myeloma, renal cell carcinoma, and colorectal cancer." (PMID 20823887, 2010). "IGF-1 and IL-6 have been extensively described as paracrine myeloma growth factors." (PMID 20465808, 2010). "Furthermore, IL-6 has previously also been shown to phosphorylate Shp2 in the myeloma cell line MM1.S." (PMID 19187270, 2009). "The main finding reported here is that IL-6-induced proliferation may be dependent on c-Met signaling in myeloma cells." (PMID 19187270, 2009).
myeloma (continued). "Thalidomide and the newer IMiDs have also been shown to significantly decrease the expression of angiogenic factors VEGF and Interleukin-6 (IL-6) in multiple myeloma; thereby reducing angiogenesis and hence contributing to clinical activity in multiple myeloma." (PMID 19674465, 2009). "It is possible that similar mechanisms are active in myeloma cells, and may explain why we observed activation of p50 in IH-1 after IL-6 stimulation." (PMID 19191868, 2009). "We exposed ten haematological cancer cells from lymphoma, myeloma, or leukemia origins to cytotoxics or ionizing radiations and assessed the effects of anti–IL-6 antibody addition on cell proliferation, apoptosis, or IL-6 signaling." (PMID 19956602, 2009). "IL-6 is an essential growth factor for myeloma cells and promotes their survival." (PMID 19152712, 2009). "It is therefore tempting to speculate that the nuclear presence of Bcl-3 as after IL-6 stimulation activates a different set of genes than activation of the classical and/or alternative NFκB pathway in myeloma cells." (PMID 19191868, 2009). "Besides, IL-6 promotes the proliferation of haematological malignancies (leukemia, lymphoma and myeloma), and solid tumours (breast and renal adenocarcinoma or Kaposi sarcoma), through an intracrine, autocrine and paracrine mode of action." (PMID 19956602, 2009). "IL-6 inhibits the apoptosis of malignant myeloma cells and helps in their proliferation." (PMID 19674465, 2009). "Following the precise identification of tumour cell dependence for IL-6 (expression of IL-6 and its receptor IL-6R) in a panel of ten cell lines (of myeloma, leukemia or lymphoma origins), we determined their individual response to different doses of radiations and chemotherapeutic drugs." (PMID 19956602, 2009). "In addition, myeloma cells are also particularly dependent upon NF-κB to produce essential growth factors [especially inerleukin 6 (Il-6)]; when NF-κB is inactive, the growth of myeloma cells is depressed." (PMID 17987322, 2008). "Myeloma cells adhere to the stromal cells and induce secretion of OAFs including interleukin (IL)-6, IL-1, tumor necrosis factor (TNF), IL-11, macrophage inflammatory protein-1α (MIP-1α), hepatocyte growth factor (HGF), parathyroid hormone-related peptide (PTHrP), and others." (PMID 18577267, 2008). "In multiple myeloma, for example, the inhibition of IL-6 receptor signaling through STAT3 was shown to induce apoptosis, an indication that IL-6-mediated STAT3 activation contributes to the pathogenesis of multiple myeloma by increasing the survival potential of tumor cells." (PMID 17324269, 2007). "Adhesion of multiple myeloma cells to stromal cells triggers IL-6 secretion by the stromal cells." (PMID 17374166, 2007). "Interestingly, in certain myeloma and prostate cancer cell lines, IL-6 has been identified as the main cytokine responsible for Stat3 activation induction." (PMID 17925034, 2007). "Several factors besides IL-6 contribute to myeloma cell proliferation." (PMID 15970928, 2005). "We then tested the effects of Atiprimod on the IL-6-responsive myeloma cell line MM-1." (PMID 15970928, 2005). "The immunomodulatory drugs (IMiDs) are 50 000 times more potent at inhibiting TNF secretion, more potent inducers of T-cell proliferation with IFN and IL-2 secretion, and inhibitors of IL-1B and IL-6 secretion, and in in vitro studies demonstrate an increased myeloma cell kill." (PMID 15655538, 2005). "In addition to being crucial for all stages of platelet generation and proliferation, a number of cytokines, including thrombopoietin (TPO), interleukin-6 (IL-6), interleukin-11 (IL-11), and interleukin-1b (IL-1b), are also involved in the pathology of myeloma." (PMID 38818376, 2024). "However, MDSCs and certain cytokines from myeloma cells like IL-6, IL-10, and TGF-β." (PMID 38900304, 2024). "IL-6 might also affect sHLA-G expression and support formation of new vasculature in myeloma." (PMID 38877399, 2024).